TRBV7-2 (T cell receptor beta variable 7-2)
Description:
V region of the variable domain of T cell receptor (TR) beta chain that participates in the antigen recognition. Alpha-beta T cell receptors are antigen specific receptors which are essential to the immune response and are present on the cell surface of T lymphocytes. Recognize peptide-major histocompatibility (MH) (pMH) complexes that are displayed by antigen presenting cells (APC), a prerequisite for efficient T cell adaptive immunity against pathogens. Binding of alpha-beta TR to pMH complex initiates TR-CD3 clustering on the cell surface and intracellular activation of LCK that phosphorylates the ITAM motifs of CD3G, CD3D, CD3E and CD247 enabling the recruitment of ZAP70. In turn ZAP70 phosphorylates LAT, which recruits numerous signaling molecules to form the LAT signalosome. The LAT signalosome propagates signal branching to three major signaling pathways, the calcium, the mitogen-activated protein kinase (MAPK) kinase and the nuclear factor NF-kappa-B (NF-kB) pathways, leading to the mobilization of transcription factors that are critical for gene expression and essential for T cell growth and differentiation. The T cell repertoire is generated in the thymus, by V-(D)-J rearrangement. This repertoire is then shaped by intrathymic selection events to generate a peripheral T cell pool of self-MH restricted, non-autoaggressive T cells. Post-thymic interaction of alpha-beta TR with the pMH complexes shapes TR structural and functional avidity.
Synonyms: TRBV72; TCRBV6S5A1N1; TCRBV7S2; TCRBV6S5A2
Gene: T-cell receptor variable (V) gene on chromosome 7 (142,352,819 to 142,353,358, forward strand). Ensembl gene ENSG00000282939.
Subcellular location: Cell membrane
Gene Ontology:
Biological process: cell surface receptor signaling pathway
Cellular component: plasma membrane
Homologues: Orthologues: macaque TRBV7-2 (89% identical). Paralogues in human: TRBV7-3 (83% identical), TRBV7-1 (78% identical), TRBV7-6 (72% identical), TRBV7-7 (72% identical), TRBV7-4 (70% identical), TRBV7-9 (67% identical), TRBV11-2 (63% identical), TRBV11-1 (62% identical), TRBV11-3 (61% identical), TRBV12-4 (57% identical), TRBV14 (57% identical), TRBV12-3 (56% identical), and 39 more.
Diseases named in the same sentence as TRBV7-2 in open-access papers:
TRBV7-2 is named in the same sentence as 2 diseases in open-access papers, as found by Europe PMC text mining. Sharing a sentence is not in itself a finding about the gene and the disease. The quoted sentences say what the papers report.
bacterial infection (1 paper, 2023). "PRP also upregulated the genes involved in the beta chain of the T cell receptor (TRBV3‐1, TRBV6‐5, TRBV7‐2, TRBV27, TRBC2, and TRBJ2‐3), which is responsible for antigen recognition and activation of cellular immunity during bacterial infection." (PMID 36704119, 2023).
TRBV7-2 also shares sentences with these, for which no sentence is quoted: COVID-19 (1 paper).